ALK (ALK receptor tyrosine kinase)
Diseases named in the same sentence as ALK in open-access papers (continued):
Sharing a sentence is not in itself a finding about the gene and the disease.
non-small cell lung carcinoma (continued). "Additionally, the chromosomal rearrangement of the ALK gene to various partners leads to a constitutive activation of ALK tyrosine kinase and represents a carcinogenic mechanism found in various cancer type including non-small-cell lung cancer and thyroid cancer." (PMID 32235612, 2020). "It has been reported that an exosome-based detection of EGFR T790M in plasma from non-small cell lung cancer patients (NSCLC) may benefit from ALK (anaplastic lymphoma kinase) inhibitor therapy whose tissue samples are not available or who are unable or unwilling to undergo repeat biopsy." (PMID 33490601, 2020). "On a large group of patients with non-small-cell lung cancer, Mezequita investigated the relationship between the intensity of radon exposure and the occurrence of specific types of mutations such as EGFR, BRAF, KRAS and HER2, as well as ALK and ROS1 rearrangements." (PMID 33327615, 2020). "Besides, selective anaplastic lymphoma kinase (ALK) inhibitors is a first-line therapy for nucleophosmin (NPM)-ALK-positive T cell lymphoma and echinoderm microtubule-associated protein like 4 (EML4)-ALK-positive non-small cell lung cancer (NSCLC)." (PMID 32493414, 2020). "Crizotinib is an effective multi-target kinase inhibitor, approved against anaplastic lymphoma kinase (ALK)- or ROS proto-oncogene 1 (ROS-1)-positive non-small cell lung carcinoma (NSCLC); however, its application is accompanied by serious side effects." (PMID 31717403, 2019). "Indeed, considering its tremendous improvement in first-line treatment compared to other ALK TKIs, alectinib should currently be the first option from all aspects for treatment-naive patients with advanced non-small cell lung cancer harboring ALK rearrangement." (PMID 31023335, 2019). "Activated ALK acts as an oncogenic driver in anaplastic large cell lymphoma (ALCL), non-small cell lung carcinoma (NSCLC) and neuroblastoma and is linked to poor clinical outcome, especially in high risk neuroblastoma." (PMID 31334113, 2019). "A chromosomal inversion leading to the fusion of the anaplastic lymphoma kinase (ALK) gene with the echinoderm microtubule-associated protein-like 4 (EML4) gene was identified in 2007, resulting in the EML4-ALK fusion protein, a therapeutic target in advanced non-small-cell lung cancer (NSCLC)." (PMID 29662531, 2018). "The ALK/MET/ROS1 inhibitor crizotinib is approved for the treatment of non-small cell lung carcinoma (NSCLC) with ALK translocations and is also being tested in neuroblastoma (clinical trial: NCT00939770)." (PMID 29515255, 2018). "It demonstrates that ALK-rearrangement may predict a favorable response to the therapy of bevacizumab combined with pemetrexed in advanced non-small cell lung cancer and this combination may be a reasonable choice for advanced ALK-rearrangement NSCLC patient when ALK-TKIs treatment failed." (PMID 29318404, 2018). "Anaplastic lymphoma kinase (ALK) inhibitors are the mainstay treatment for patients with non-small cell lung carcinoma (NSCLC) harboring a rearrangement of the ALK gene or the ROS1 oncogenes." (PMID 29774128, 2018). "As anaplastic lymphoma kinase (ALK)-tyrosine kinase inhibitors (TKIs) dramatically improve progression-free survival compared to cytotoxic agents, ALK-TKIs are commonly used for ALK fusion protein-positive non-small cell lung cancer unless the tumor becomes resistant to the drug." (PMID 29732013, 2018). "A decade ago, genomic rearrangements in the anaplastic lymphoma kinase (ALK) receptor tyrosine kinase were identified in a subset of non-small cell lung carcinoma (NSCLC) patients." (PMID 29455675, 2018). "Therefore, great efforts are now aimed at pharmacologically inhibiting ALK activity in NB cells by taking advantage of small molecule inhibitors such as crizotinib, an FDA-approved anticancer drug that exhibited efficacy in non-small cell lung cancers harboring ALK translocations." (PMID 28915608, 2017).
non-small cell lung carcinoma (continued). "Patients with advanced-stage non-small cell lung carcinoma (NSCLC) harboring an ALK rearrangement, detected from a tissue sample, can benefit from targeted ALK inhibitor treatment." (PMID 28805682, 2017). "Since then, ALK has been found to be involved in several other cancers, mainly as a consequence of different chromosomal translocations such as those reported in inflammatory myofibroblastic tumors, non-small cell lung cancer and diffuse large B-cell lymphomas." (PMID 28915608, 2017). "Anaplastic lymphoma kinase (ALK) gene fusion has been reported in 3∼5% non-small cell lung carcinoma (NSCLC) patients, and polymerase chain reaction (PCR) is commonly used to detecting the gene status, but the diagnostic capacity of it is still controversial." (PMID 29088875, 2017). "However, other ALK fusion partners have been described in non-small cell lung cancer and other tumor types, limiting the possibility to found all ALK translocations that may be present in CRC specimens." (PMID 24691006, 2014). "Recently, a novel gene fusion involving ALK and echinoderm microtubule-associated protein-like 4 (EML4) was discovered in non-small cell lung carcinoma (NSCLC)." (PMID 24156086, 2013). "ALK-rearranged non-small cell lung cancer (NSCLC) represents a paradigm of precision oncology, but acquired resistance to second-generation ALK tyrosine kinase inhibitors (TKIs) such as alectinib remains inevitable." (PMID 41726081, 2026). "Most of the studies proposed the AI-based models for the identification of Epidermal growth factor receptor (EGFR) biomarker in non-small cell lung cancer (NSCLC), followed by Programmed death-ligand 1 (PD-L1) and anaplastic lymphoma kinase (ALK)." (PMID 40078179, 2025). "Over the past two decades, marked progress has been made in treating non-small cell lung cancer (NSCLC) patients with EGFR-, ALK-, ROS1- and KRASG12C-targeted inhibitors." (PMID 40893689, 2025). "In current study, we focus on the oncogenic mechanism in non-small cell lung cancer patients without typical gene mutations or rearrangements/fusion and report a non-canonical role of RNase1, a human ribonuclease superfamily protein, as a ligand of wild-type ALK." (PMID 40246819, 2025). "Lastly Crizotinib, targeting ALK and ROS1 in non-small cell lung cancer, frequently leads to visual disturbances." (PMID 41568391, 2025). "For instance, reduced m6A levels enhances the therapeutic efficacy of crizotinib, an ALK/ROS1/c-MET kinase inhibitor, in the treatment of non-small cell lung cancer (NSCLC) with high c-MET expression." (PMID 40533443, 2025). "Lorlatinib, another ALK inhibitor that also inhibits ROS1 (a receptor tyrosine kinase), was approved in 2021 by the FDA for metastatic ALK-positive non-small cell lung cancer." (PMID 40507292, 2025). "Using the SWISS-MODEL server, we generated accurate 3D models for EGFR, ALK, KRAS, and PD-1, which represent key oncogenic and immunomodulatory targets in non-small cell lung cancer (NSCLC)." (PMID 40927719, 2025). "In non-small cell lung cancer (NSCLC), anaplastic lymphoma kinase (ALK) gene rearrangements are commonly detected in lung adenocarcinoma." (PMID 40052122, 2025). "Anaplastic lymphoma kinase (ALK) is activated predominantly as an EML4-ALK fusion protein, especially in non-small cell lung cancer (NSCLC), and promotes cancer cell proliferation." (PMID 40872476, 2025). "ALK: anaplastic lymphoma kinase; NSCLC: non-small cell lung cancer; ADC: adenocarcinoma; SRT: stereotactic radiotherapy." (PMID 39087188, 2024). "Among patients with non-small cell lung cancer (NSCLC), approximately 3%-7% harbor anaplastic lymphoma kinase (ALK) gene fusions." (PMID 39962851, 2024). "Paradigm defining examples are targeted therapies directed against non-small cell lung cancer (NSCLC) subtypes with oncogenic alterations in EGFR, ALK and KRAS." (PMID 38702301, 2024).
non-small cell lung carcinoma (continued). "Entrectinib is an inhibitor of NTRK, ALK, and ROS1 that is currently approved in patients with ROS1-positive non-small cell lung cancer and patients with solid tumors and NTRK gene fusions." (PMID 38438731, 2024). "This drug demonstrates efficacy in treating ALK-positive and ROS1-positive non-small cell lung cancer (NSCLC)." (PMID 39001541, 2024). "Given that the majority of ALK-positive non-small cell lung carcinomas (NSCLC) are LADC, the benefits of TKIs for patients with ALK-positive lung squamous cell carcinoma (LSCC) and the optimal treatment strategy for these patients remain a subject of debate." (PMID 38380327, 2024). "According to previous reports, ALK inhibitors are effective against anaplastic large cell lymphoma (ALCL), ALK-positive non-small cell lung cancer (NSCLC), and ALK+ LBCL." (PMID 39906668, 2024). "Cell-level studies have shown that alectimib can inhibit the activation of ALK and downstream STAT3 and AKT signaling pathways in NCL-H2228 non-small-cell lung cancer cells." (PMID 38674402, 2024). "As an oral small-molecule tyrosine kinase inhibitor, Crizotinib, targeting the ALK, ROS1 and MET tyrosine kinases, is well approved to induce clinically significant responses in non-small cell lung cancer." (PMID 37950305, 2023). "The ALK, ROS1 and RET kinase fusion are crucial biomarkers that can predict the function of tyrosine kinase inhibitors (TKIs) in the non-small-cell-lung cancer (NSCLC)." (PMID 37091783, 2023). "These PROTACs were highly effective in degrading wild type ALK (DC50 of 10nM in H3122 cells and DC5 40 nM in Karpas 299 cells) and inhibiting the proliferation of anaplastic large cell lymphoma and non-small-cell lung cancer." (PMID 36986673, 2023). "Lorlatinib, a third-generation ALK tyrosine kinase inhibitor (TKI), received its initial FDA approval in November 2018 as a treatment for ALK-positive metastatic non-small cell lung cancer." (PMID 37513921, 2023). "In a small case series of non-small-cell lung cancer patients with monoclonal concomitant EGFR and ALK alterations, ALK inhibitors appeared to be effective for patients with co-alterations, but our patient eventually progressed while on lorlatinib." (PMID 37835855, 2023). "The development of targeted therapies has led to personalized medicine for advanced non-small cell lung cancer (NSCLC), particularly in lung adenocarcinoma (ADC) with actionable genetic alterations, such as EGFR, ALK, KRAS, and ROS1." (PMID 37345086, 2023). "The translocation of anaplastic lymphoma kinase (ALK) was originally identified in anaplastic large-cell lymphoma (ALCL) and subsequently in non-small cell lung carcinoma (NSCLC)." (PMID 37894456, 2023). "The discovery of the rearrangement of ALK and ROS1 has led the era of precision medicine for advanced non-small cell lung cancer (NSCLC)." (PMID 37036582, 2023). "Brigatinib, a second-generation ALK inhibitor, outperformed crizotinib in the ALTA-1 study for PFS and health-related quality of life (QoL) in advanced ALK drug-naive ALK-positive non-small cell lung cancer." (PMID 36900362, 2023). "In non-small cell lung carcinoma (NSCLC), targeted therapies are mainly directed toward specific altered genes that have been thoroughly analyzed, including EGFR, ALK, ROS1, and RET." (PMID 37999148, 2023). "Second-generation ALK inhibitors, such as alectinib and brigatinib have been designed with an enhanced BBB penetration to treat ALK-driven non-small cell lung cancer (NSCLC) with CNS metastasis." (PMID 37781183, 2023). "For example, targeting ALK has shown success in treatments of ALK(+) non-small cell lung cancers and also in childhood anaplastic large cell lymphoma (ALCL) and inflammatory myofibroblastic tumor using the ALK inhibitor crizotinib." (PMID 36900212, 2023).
non-small cell lung carcinoma (continued). "In addition to common EGFR activation mutations, targets such as ALK rearrangement, ROS1 rearrangement, RET rearrangement, BRAF V600E, MET exon 14 skip mutation, KRAS G12C, etc. have been gradually approved for targeted drug application in advanced non-small cell lung cancer." (PMID 38023198, 2023). "Crizotinib, a selective small-molecule tyrosine kinase inhibitor (TKI) of cMET, anaplastic lymphoma kinase (ALK), and reactive oxygen species (ROS1) is approved for ALK or ROS1-positive metastatic non-small cell lung cancer." (PMID 36106113, 2022). "ALK fusion genes drive tumorigenesis across a variety of different malignancies including anaplastic large cell lymphoma (ALCL), non-small-cell lung cancer (NSCLC) and inflammatory myofibroblastic tumor (IMT)." (PMID 35689207, 2022). "It is currently FDA-approved for treating metastatic non-small cell lung cancer with ALK or ROS-1 positivity per an FDA-approved test, ALK-positive anaplastic large cell lymphoma, and ALK-positive inflammatory myofibroblastic tumors." (PMID 36172151, 2022). "In a phase II clinical trial including patients with non-small cell lung cancer (NSCLC) and ALK rearrangement, brigatinib resulted in elevated blood pressure in 20% of the participants." (PMID 35269958, 2022). "Data from 3 commercial vendors showed that the prevalence of ALK and ROS1 rearrangements in histologies other than non-small cell lung cancer and lymphoma was rare (0.1% and 0.4% respectively)." (PMID 35233056, 2022). "For example, although Swedish non-small cell lung cancer guidelines recommend NGS-based genomic testing for EGFR, KRAS, BRAF, ALK, NTRK, and ROS1, guidelines in Norway only include EGFR, ALK, and ROS1." (PMID 35055387, 2022). "Immunoprecipitation followed by phosphoproteomics using mass spectrometry demonstrated that RTKs including ALK, ROS fusion proteins, PDGFRα, and DDR were found to be highly phosphorylated in non-small cell lung carcinoma cell lines and tumor samples." (PMID 35711942, 2022). "Genetic alterations, including mutation, gene amplification, or chromosomal rearrangement in the anaplastic lymphoma kinase (ALK) gene, are detected in 3 to 8% of patients with non-small cell lung cancer (NSCLC)." (PMID 36424628, 2022). "Rearrangement in the anaplastic lymphoma kinase (ALK) gene occurs in 2–5% of non-small-cell lung cancer (NSCLC) cases and leads to constitutive activation of the ALK kinase, which promotes ALK-driven tumorigenesis." (PMID 35720977, 2022). "On the contrary, another study showed that treatment of NCI-H2228, a human non-small cell lung carcinoma cell line, with CH5424802 (a selective ALK inhibitor) led to reduction in p-Akt expression." (PMID 36425467, 2022). "Currently, the best studied ALK fusions are NPM1-ALK in anaplastic large-cell lymphoma (ALCL) and EML4-ALK in non-small cell lung cancer (NSCLC), which harbor ALK fusions in approximately 5% of cases." (PMID 35204520, 2022). "Researchers also found that in non-small cell lung cancer, EGFR-mutant and ALK-rearranged tumors responded poorly to anti-PD-1/PD-L1 treatment and exhibited higher infiltrations of CD4+ memory resting T cells." (PMID 36588538, 2022). "Abnormal fusion genes such as ALK, ROS1, and NTRK are commonly observed in subsets of patients with non-small cell lung cancer (NSCLC)." (PMID 33627640, 2021). "Crizotinib is currently used to treat ALK-rearranged cancers, such as anaplastic large-cell lymphoma (ALCL) and non-small cell lung cancer (NSCLC), and crizotinib has demonstrated efficacy in treating ALK-positive IMT as well." (PMID 35126101, 2021). "Treatment planning for non-small cell lung cancer requires testing for EGFR, ALK, ROS1, BRAF, MET, RET and KRAS gene alterations." (PMID 34681592, 2021).
non-small cell lung carcinoma (continued). "Recently, a phase III CROWN trial compared the efficacy of two anaplastic lymphoma kinase (ALK) inhibitors and demonstrated that lorlatinib displayed clinical improvement over crizotinib for advanced non-small cell lung cancer (NSCLC) patients." (PMID 34136409, 2021). "Anaplastic lymphoma kinase (ALK) fusion gene, as a tumor driver gene, was crucial for the occurrence and development of non-small cell lung cancer (NSCLC)." (PMID 34670356, 2021). "The FDA authorized crizotinib to treat anaplastic lymphoma kinase (ALK)-rearranged non-small cell lung cancer (NSCLC) in August 2011, only 4 years after the first published report of an ALK-rearranged NSCLC." (PMID 33941195, 2021). "Anaplastic Lymphoma Kinase (ALK) is the dominant driver oncogene in several tumors, including Anaplastic Large-Cell Lymphoma (ALCL), Non-Small Cell Lung Cancer (NSCLC) and others." (PMID 34680298, 2021). "Anaplastic lymphoma kinase (ALK) is validated as a therapeutic molecular target in multiple malignancies, such as non-small cell lung cancer (NSCLC)." (PMID 35004700, 2021). "The possibility of molecular testing, including epidermal growth factor receptor (EGFR), anaplastic lymphoma kinase (ALK), and programmed death ligand 1 (PD-L1), was identified with non-small cell lung cancer (NSCLC) tissue obtained using ENB." (PMID 34441366, 2021). "Echinoderm microtubule-associated protein-like 4 (EML4) is the canonical anaplastic lymphoma kinase (ALK) fusion partner in non-small cell lung cancer (NSCLC), and ALK-positive patients showed promising responses to ALK tyrosine kinase inhibitors (TKIs)." (PMID 33363027, 2020). "In non-small cell lung carcinoma (NSCLC), the gene fusions of ALK, NTRK, RET, and ROS1 are detected with the approximate frequencies of 4–6, 1, 1–2, and 1–2%, respectively." (PMID 32328458, 2020). "The existence of HIV infection should not negatively influence the search for other druggable targets, such as anaplastic lymphoma kinase (ALK) rearrangement, already described in PLWH affected by non-small cell lung cancer (NSCLC)." (PMID 32111093, 2020). "The kinase targets in non-small cell lung cancer (NSCLC) include epidermal growth factor receptor (EGFR), anaplastic lymphoma kinase (ALK) and ROS proto-oncogene 1 (ROS1)." (PMID 32595510, 2020). "In particular, the discovery of EML4-ALK has led to accelerated approval of several ALK inhibitors by the U.S. Food and Drug Administration (FDA) for the treatment of non-small cell lung cancer with stunning clinical responses." (PMID 32771039, 2020). "Tumor tissue biopsy is often limited for non-small cell lung cancer (NSCLC) patients and alternative sources of tumoral information are desirable to determine molecular alterations such as anaplastic lymphoma kinase (ALK) rearrangements." (PMID 32549278, 2020). "Anaplastic lymphoma kinase (ALK) rearrangement, a key oncogenic driver in a small subset of non-small cell lung cancers, confers sensitivity to ALK tyrosine kinase inhibitors (TKIs)." (PMID 31827192, 2019). "Anaplastic lymphoma kinase (ALK) rearrangements lead to an in-frame fusion protein with oncogenic activity and are detected in approximately 5% of non-small cell lung cancer (NSCLC) cases." (PMID 30866974, 2019). "Anaplastic lymphoma kinase (ALK) inhibitors are currently being considered in neuroblastoma (NB), but its acquired resistance is reported in non-small cell lung cancers." (PMID 31780656, 2019). "Crizotinib, a first-generation anaplastic lymphoma kinase (ALK) inhibitor, and ceritinib and alectinib, the second-generation ALK inhibitors, have been used as the first-line treatment for non-small-cell lung cancer (NSCLC) carrying ALK or ROS1 rearrangements." (PMID 30949374, 2019). "Activation of the anaplastic lymphoma kinase (ALK) gene has been found in several human cancers, including non-small-cell lung cancer (NSCLC)." (PMID 30608384, 2019).